BLM (BLM RecQ like helicase)
Diseases named in the same sentence as BLM in open-access papers (continued):
Sharing a sentence is not in itself a finding about the gene and the disease.
Bloom syndrome (continued). "The Saccharomyces cerevisiae RecQ helicase Sgs1 is orthologous to human BLM, defects in which cause the cancer-prone Bloom's Syndrome." (PMID 30916344, 2019). "Inherited mutations in RecQ helicases result in several genetic diseases, including Bloom Syndrome (mutations in BLM), Werner Syndrome (mutations in WRN), Rothmund-Thomson Syndrome (mutations in RECQL4), and other diseases, including cancer." (PMID 31772289, 2019). "BLM is mutated in Bloom’s syndrome—an inherited disorder characterized by short stature, UV sensitivity, and a greatly increased risk of cancer." (PMID 31546714, 2019). "On the other hand, it is well known that BLM mutations lead to Bloom Syndrome, a disease characterized by growth retardation and predisposition to cancer." (PMID 30800220, 2019). "The BLM p.Gln548Ter mutation is the most common cause of Bloom syndrome in Slavic individuals, including Poland and Russia." (PMID 31614901, 2019). "This mutation is a cause of Bloom syndrome, as we and others diagnosed patients with Bloom syndrome homozygous for this protein-truncating variant of BLM." (PMID 31614901, 2019). "Bloom’s syndrome (BS) is an autosomal recessive disease, caused by mutations in the BLM gene located at 15q26." (PMID 29098565, 2018). "RPA physically and functionally interacts with the human RecQ helicase BLM that is mutated in Bloom’s syndrome (BS), a growth retardation disorder characterized by elevated sister chromatid exchange and a strong incidence of cancer." (PMID 28594346, 2017). "Another class of G4-unwinding helicases includes RecQ-related helicases WRN (Werner’s syndrome) and BLM, whose mutations cause cancer susceptible disorders Werner and Bloom syndromes, respectively." (PMID 28272375, 2017). "Premature stop codons in BLM, which encodes a DNA helicase that functions in DNA double‐strand‐break repair, make up the vast majority of Bloom syndrome mutations, with only 13 single amino acid changes identified in the syndrome." (PMID 26788541, 2016). "Disruption of the BLM gene causes Bloom's syndrome, a disease that is marked by a strong predisposition to genomic instability and cancer." (PMID 26871287, 2016). "Bloom syndrome is caused by defects in the BLM DNA helicase, which “dissolves” recombination intermediates, such that loss of BLM results in a hyperrecombination phenotype and genomic instability, including radial chromosome formation." (PMID 27428646, 2016). "Bloom’s syndrome, an autosomal recessive human disorder caused by mutated recQ-like helicase BLM, presents with growth defects suggestive of underlying defects in rRNA transcription." (PMID 27657136, 2016). "Mutations in the human RecQ helicase, BLM, causes Bloom Syndrome, which is a rare autosomal recessive disorder and characterized by genomic instability and an increased risk of cancer." (PMID 27083049, 2016). "Bloom syndrome (BS), an autosomal recessive disorder of the BLM gene, predisposes sufferers to various cancers." (PMID 27601585, 2016). "In this context, Smc5/6 is crucial to compensate for deficiencies in the RecQ helicase Sgs1/BLM, mutated in cancer-prone Bloom syndrome patients, likely by its role in modulating resolution or remodeling of the emerging recombination intermediates." (PMID 26698660, 2015). "To illustrate the steps taken, we describe below the variant selection for the Bloom syndrome gene (BLM) in detail." (PMID 26247052, 2015). "Germline mutation in BLM is the cause of Bloom syndrome, a rare disease associated with cancer predisposition." (PMID 26437225, 2015). "Several mutations of the RecQ helicase gene BLM cause Bloom syndrome (BS), which is a hereditary disease and associated with a predisposition for cancer." (PMID 24575106, 2014). "Our results showed that SQ and SCLC had overexpressed genes throughout the pathway with 10 of 11 genes overexpressed including the very important BRCA2, RAD51 paralogs and BLM (Bloom syndrome mutated)." (PMID 25325012, 2014).
Bloom syndrome (continued). "BLM, a RecQ family DNA helicase mutated in Bloom's Syndrome, participates in homologous recombination at two stages: 5′ DNA end resection and double Holliday junction dissolution." (PMID 25200081, 2014). "Defects in the RecQ-type helicase BLM lead to Bloom's syndrome, a human disorder associating genomic instability and cancer predisposition." (PMID 25313826, 2014). "The Arabidopsis RecQ helicase RECQ4A is the functional counterpart of human BLM, which is mutated in the genetic disorder Bloom’s syndrome." (PMID 24174542, 2014). "In the autosomal recessive, clinical entity Bloom's syndrome (BS), genome integrity is strikingly destabilized due to null mutations in the gene BLM." (PMID 24027577, 2013). "- BLM: Another such gene that has recently been implicated in breast cancer susceptibility, is BLM, the gene mutated in Bloom’s Syndrome." (PMID 24025454, 2013). "Bloom syndrome is a rare, autosomal recessive, chromosomal instability disorder caused by mutations in the BLM gene that increase the risk of developing neoplasias, particularly lymphomas and leukemias, at an early age." (PMID 24377487, 2013). "Defects in the human BLM gene cause Bloom syndrome, notable for early development of tumors in a broad variety of tissues." (PMID 23110454, 2012). "Our analysis identified families with heterozygous, deleterious mutations in the DNA repair genes FANCC and BLM, which are responsible for the autosomal recessive disorders Fanconi Anemia and Bloom syndrome." (PMID 23028338, 2012). "Bi-allelic mutations in the BLM gene give rise to Bloom syndrome, a rare cancer predisposition disorder in humans." (PMID 22911760, 2012). "This point is of particular interest because BLM deficiency causes Bloom’s syndrome, an autosomal recessive disease displaying one of the strongest known correlations between chromosomal instability and an increase in the risk of cancer at an early age." (PMID 22563370, 2012). "Remarkably, two families carried overtly deleterious mutations in the Fanconi anemia (FA) gene FANCC and one family carried an overtly deleterious mutation in the Bloom's syndrome (BS) gene BLM." (PMID 23028381, 2012). "Mutations in BLM cause Bloom syndrome, a rare disorder associated with cancer predisposition and premature aging." (PMID 22183041, 2011). "Genome instability is associated with human cancers and chromosome breakage syndromes, including Bloom's syndrome, caused by inactivation of BLM helicase." (PMID 22040455, 2011). "Mutations altering BLM function are associated with highly elevated cancer susceptibility (Bloom syndrome)." (PMID 19432957, 2009). "The gene mutated in Bloom's syndrome, BLM, is important in the repair of damaged replication forks, and it has both pro- and anti-recombinogenic roles in homologous recombination (HR)." (PMID 19956565, 2009). "Previous studies have implicated the DNA-processing enzyme BLM in the regulation of homologous recombination; BLM is defective in Bloom's syndrome, which is characterized by excess recombination and cancer susceptibility." (PMID 19956565, 2009). "Our finding is in line with the observation that individuals with Blooms syndrome carrying mutations in BLM, essential for the homologous recombination complex, show elevated risk for various cancer types." (PMID 19432957, 2009). "Germline mutations in the BLM gene in humans give rise to Bloom’s syndrome (BS), an autosomal recessive condition characterized by pre- and post-natal growth retardation, microcephaly, skin pigmentation abnormalities, and a strong predisposition to the development of cancer." (PMID 40355560, 2025). "Finally, BLM encodes a DNA helicase that helps maintain the fidelity of homologous recombination and is mutated in Bloom syndrome, characterized by growth retardation, immunodeficiency, and cancer susceptibility." (PMID 39138582, 2024).
Bloom syndrome (continued). "The worldwide incidence of Bloom syndrome due to biallelic causative variants in the BLM gene is unknown, ~300 cases have been reported so far in databases and in the medical literature." (PMID 37052241, 2023). "The study emphasizes the crucial regulatory role of rG4s and related helicases in SG dynamics and suggests that additional explorations of RNA-associated BLM functions are warranted in the context of G4-associated genetic diseases and specifically in Bloom's syndrome." (PMID 37503837, 2023). "The pathogenic variants including missense and truncating sequence variants and intragenic deletions of the BLM gene have been confirmed as the molecular genetic cause of Bloom syndrome, an autosomal recessive disorder affecting multiple body tissues and organ systems." (PMID 37052241, 2023). "In contrast, Bloom syndrome (BS), which is caused by mutations in BLM, is a developmental disorder that typically includes microcephaly, short stature, immunodeficiency, skin hyper- or hypopigmentation, photosensitivity, facial erythema, and an increased predisposition for developing cancer." (PMID 35025765, 2022). "Mutations in BLM cause the autosomal recessive disease Bloom syndrome (BS)." (PMID 36499126, 2022). "This hypothesis has been proved right by others for a different DNA helicase termed BLM involved in Bloom’s syndrome in humans, which is associated with mild lymphopenia and an increased number of infections." (PMID 36330520, 2022). "Interestingly, patients with the Bloom’s syndrome have an average lifespan of 25 years, and BLM-deficient cells display a high sister chromatid exchange (SCE) ratio that is positively linked to mutation rate and cancer incidence." (PMID 36611939, 2022). "In this study, we have identified abnormalities in Bloom-syndrome-patient-derived cells and BLM-knockout cells that include increased ROS that causes DNA base damage and reduced DNA replication speed, increased mitochondrial mass and TFAM expression, and mitochondrial fragmentation." (PMID 33495511, 2021). "Bloom’s syndrome, caused by null or missense mutations in the BLM gene, is characterized by genomic instability, increased occurrence of sister-chromatid exchanges, increased cancer susceptibility, insulin resistance and immunodeficiency, features that are also associated with normal aging." (PMID 34506302, 2021). "This study identifies mitochondria-associated abnormalities in Bloom syndrome patient-derived and BLM-knockout cells and we discuss how these abnormalities may contribute to Bloom syndrome." (PMID 33495511, 2021). "Another recent study suggests that impairment of mitochondrial dynamics during mitosis could contribute to phenotypes associated with the rare genetic disorder Bloom Syndrome (BS) which is linked to loss of function mutations in the BLM gene." (PMID 34805174, 2021). "We have found that loss of RPA association with the Bloom syndrome complex constitutes a clear separation-of-function mutation with regard to the cellular functions of BLM, given that RPA-binding is required for replication fork restart but not for other roles in DNA repair." (PMID 33500419, 2021). "Also, patients with Bloom syndrome (BS, an autosomal recessive genetic disorder) lack or have a mutated BLM-RecQ-like helicase crucial for genome integrity or stability." (PMID 33643304, 2020). "Similarly, individuals with homozygous mutation in BLM, another central DNA damage related gene, develop the Bloom’s syndrome that is characterized by predisposition to cancer, growth deficiency and genomic instability." (PMID 31889988, 2019). "As SDSA is mediated by BLM, the gene affected in Bloom syndrome, and loss of BLM results in rDNA instability, one can speculate that rDNA breaks are preferably repaired through this pathway, also to prevent loss of rDNA repeats." (PMID 30556094, 2019).
Bloom syndrome (continued). "Importantly, Saccharomyces cerevisiae Sgs1 is orthologous to human BLM and sgs1Δ mutations phenocopy many of the genome integrity defects observed in cells from Bloom syndrome patients." (PMID 30916344, 2019). "Interestingly, other key members of the same protein family have been associated with well-known recessive cancer predisposition syndromes (BLM, Bloom syndrome; RECQL4, Rothmund–Thompson syndrome; WRN, Werner syndrome)." (PMID 30871259, 2019). "Interestingly, monoallelic mutations in RECQL1 and in the Bloom syndrome gene BLM have been described as risk factors for BrCa, although the BLM association has been contested by others." (PMID 29659569, 2018). "Mutations in BLM deleting or altering its helicase motifs and disabling its 3'-5' helicase activity may induce Bloom syndrome." (PMID 29689049, 2018). "Mutations in BLM in Bloom Syndrome patients predispose them to multiple types of cancers." (PMID 29523790, 2018). "Overall, loss of RMI2 produces a partially active BLM complex with mild features of Bloom syndrome." (PMID 27977684, 2016). "Mutations in BLM could lead to Bloom syndrome, which is an autosomal-recessive genetic disorder that is associated with increased levels of spontaneous sister-chromatid exchanges (SCEs), genome instability, as well as elevated cancer susceptibility." (PMID 26901225, 2016). "Bloom syndrome (BS) is an inherited disorder due to mutation in BLM gene." (PMID 27597923, 2016). "The only gene that is known to cause Bloom syndrome is the BLM helicase." (PMID 27977684, 2016). "Here, in addition to identifying five BLM variants incapable of complementing certain defects of Bloom syndrome cells, making them candidates for new Bloom syndrome causing mutations, we characterize a new class of BLM variants that cause some, but not all, cellular defects of Bloom syndrome." (PMID 26788541, 2016). "In the majority of persons with Bloom syndrome the BLM gene is inactivated by small insertion/deletion mutations or nonsense mutations that lead to a premature stop codon upstream or within exons 7–18, which code for the helicase core of BLM." (PMID 26788541, 2016). "Mutations in three human RecQ helicase homologs WRN, BLM and RecQ4 are related to rare genetic disorders of Werner Syndrome, Bloom Syndrome, and Rothmund-Thomson/ RAPADILINO/Baller-Gerold Syndrome, respectively, all characterized by chromosomal instability and predisposition to cancer." (PMID 24688722, 2013). "In humans defects in three of at least five functionally non-redundant genes encoding RecQ helicases are associated with severe heritable disease, i.e. Bloom's syndrome (BLM, RECQ2, RECQL3 gene), Rothmund-Thomson syndrome (RECQL4 gene) and Werner's syndrome (WRN, RECQ3, RECQL2 gene)." (PMID 22327026, 2012). "Additionally high T-SCE rates have been observed in cells with deficiencies in WRN and BLM, the genes that are defective in Werner's and Bloom's syndromes, implying a connection to premature aging." (PMID 20952810, 2010). "BLM, the helicase mutated in Bloom syndrome, is found in protein complexes together with topoisomerase IIIa (TOP3A) and a newly identified member, the RECQ-mediated genome instabilitity 1 (RMI1) protein, that process double Holliday junction intermediates into non-crossover recombinants." (PMID 19432957, 2009). "BLM dysfunction is directly linked to an autosomal recessive genetic disorder “Bloom syndrome” (BS)." (PMID 40728512, 2025). "Bloom syndrome (BS) is a rare autosomal recessive disorder caused by a loss-of-function mutation in the BLM gene, which encodes an RecQ helicase involved in DNA repair and maintenance of chromosomal stability." (PMID 38995367, 2024). "Bloom syndrome (BS) is a heritable, recessive genetic instability and cancer predisposition syndrome caused by bi-allelic loss of function mutations in the BLM gene that encodes one of the five human RECQ helicase proteins." (PMID 38994931, 2024).
Bloom syndrome (continued). "Mutations in human BLM cause Bloom syndrome (BS), an autosomal recessive disorder that leads to myriad negative health impacts including a predisposition to cancer." (PMID 36747637, 2023). "Bloom syndrome (BS) is associated with a profoundly increased cancer risk and is caused by mutations in the Bloom helicase (BLM)." (PMID 35473934, 2022). "Bloom Syndrome (BSyn) is an autosomal recessive disease caused by variants in the BLM gene, located at the 15q26.1 locus." (PMID 35782872, 2022). "Mutations in BLM lead to a rare autosomal-recessive genetic disorder, Bloom syndrome (BS; OMIM#210900)." (PMID 33718381, 2021). "Mutations of BLM in humans lead to Bloom syndrome (BS), which can result in immunodeficiency, dwarfism, sterility, premature aging, and multiple cancers, such as breast cancer." (PMID 34606619, 2021). "Mutations in WRN, BLM, and RecQL4 cause Werner syndrome (WS), Bloom syndrome (BS), and Rothmud-Thomson syndrome (RTS), respectively, which are associated with premature aging, cancer predisposition, and chromosome abnormalities." (PMID 33266355, 2020). "Variation in the BLM helicase gene resulted in defects in the DNA repair mechanism and was reported to be associated with Bloom syndrome (BS) and cancer." (PMID 32704157, 2020). "BLM is deficient in Bloom syndrome (BS), a rare genetic disease characterized by genome instability, increased sister chromatids exchanges, accumulation of micronuclei, susceptibility to cancer and immunodeficiency." (PMID 32283785, 2020). "In contrast, mutations in Bloom syndrome protein (BLM) can result in the autosomal recessive disease Bloom syndrome (BS)." (PMID 31210839, 2019). "Loss of BLM helicase function in humans results in Bloom Syndrome (BS), a rare autosomal recessive disease." (PMID 31772289, 2019). "Mutations in BLM cause Bloom syndrome (BS), a genetic disorder characterized by a strong growth deficiency, reduced fertility, diabetes, and cancer predisposition." (PMID 27664093, 2017). "Bloom syndrome (BS) is an extremely rare autosomal recessive genetic disorder caused by a mutation in the BLM gene encoding a DNA repair enzyme homology to the RecQ helicases that receives the same name of the gene." (PMID 27597923, 2016). "While mutational inactivation of WRN and BLM helicases leads to Werner (WS) and Bloom syndromes (BS) respectively, mutations in RecQL4 lead to three autosomal recessive disorders; Rothmund-Thomson syndrome, Baller-Gerold and RAPADILLINO." (PMID 23894508, 2013). "FA proteins and BLM are thought to play a role in response to replication stress, and mutations in their genes have been associated with severe human diseases, the Fanconi anaemia and Bloom syndrome (BS), characterized by genome instability and cancer predisposition." (PMID 24083238, 2013). "Bloom Syndrome (BS) is an autosomal recessive disorder due to mutation in Bloom helicase (referred in literature either as BLM helicase or BLM)." (PMID 21050475, 2010). "Together, our data substantiate a regulatory role for G4s in Bloom syndrome and support a molecular model in which unresolved G4s in BLM/-cells enhance chromatin accessibility, thereby promoting gene expression." (PMID 41867784, 2026). "Pathogenic mutations on BLM, WRN, and RECQL4 are associated with several pathological conditions, namely Bloom syndrome (BS), Werner syndrome (WS), and Rothmund-Thomson syndrome (RTS)." (PMID 40728512, 2025). "Mammalian TRF1 specifically mitigates lagging strand replication stress by promoting the recruitment of BLM (Bloom syndrome), a RecQ family helicase which is capable of unwinding G4s which would impede replisome progression." (PMID 39483338, 2024). "The Bloom syndrome gene product, BLM, a member of the highly conserved RecQ helicase family, is implicated in this process, yet its precise regulation and role remain poorly understood." (PMID 38341452, 2024). "BS is caused by mutations to BLM, which encodes the Bloom Syndrome DNA helicase (BLM)." (PMID 36747637, 2023).